IL6 (interleukin 6)
Diseases named in the same sentence as IL6 in open-access papers (continued):
Sharing a sentence is not in itself a finding about the gene and the disease.
Obesity (continued). "These authors reported that obesity was associated with heightened systemic inflammation, as noted by increases in plasma IL-6, IL-17, C-reactive protein (CRP), and prostaglandin E2 (PGE2)." (PMID 34421889, 2021). "However, our data did not support significant effects of two weeks of CR and CPI on IL-6, which was suggested an important risk marker for NAFLD in obesity." (PMID 34834448, 2021). "It suggested that obesity IL-6 might be a potential mechanism to enhance the postmenopausal, hormone-responsive BC progression via an elevated local aromatase expression." (PMID 34350120, 2021). "Obesity, especially abdominal obesity, is now considered as a chronic inflammatory state via the continuous release of proinflammatory cytokines, including tumor necrosis factor-α, interleukin 6, which favor MetS and cardiovascular diseases." (PMID 34970217, 2021). "Indeed, increased levels of TNF-α, IL-6, MMP-9, and VEGF have been extensively documented in obesity and found to be associated with metabolic inflammation, hyperglycemia, insulin resistance and progression to type-2 diabetes or metabolic syndrome." (PMID 34230580, 2021). "The obesity state can elevate proinflammatory adipokines through adipose tissue inflammation, such as interleukin-6 (IL-6), tumor necrosis factor-alpha (TNF-α) and free fatty acids (FFAs), which can induce both insulin resistance and compensatory hyperinsulinism." (PMID 34603211, 2021). "Obesity is related to a concurrent increase in ROS and expression of NADPH oxidase, and a decrease in the expression of antioxidant enzymes, which are associated with altered adiponectin, IL-6, and monocyte chemoattractant protein (MCP-1) production." (PMID 33557218, 2021). "In this first cross-sectional study, examining breast tissue-specific biomarker expression with combined obesity parameters, we found that mean expression levels of IL-6, TNF-α, and LEP were higher in the breast adipose tissue of women with WC ≥ 86 cm, regardless of BMI." (PMID 34426770, 2021). "A parallel, double-blind, placebo-controlled, randomized study reported the ability of aged garlic supplementation to modulate immune cell distribution and decrease serum tumor necrosis factor (TNF)-α and interleukin (IL)-6 levels in healthy obese adults, thus reducing obesity-induced inflammation." (PMID 34444755, 2021). "It is reported that IL-6 may affect the homeostasis of energy and glucose in obese mice through activating IL-6 trans-signaling in central nervous system, and thus IL-6 may be a potential therapeutic target in treatment of obesity." (PMID 34334083, 2021). "The inflammation caused by overnutrition or obesity is characterized by the activation of various immune cells, which release pro-inflammatory cytokines, such as tumor necrosis-alpha (TNF-α), interleukin-6 (IL-6), and C-reactive protein (CRP)." (PMID 34867458, 2021). "However, further studies are needed to clarify the role played by IL-6 and other cytokines in individuals with obesity and overweight presenting with SARS-CoV-2 infection." (PMID 33816341, 2021). "However, we recently showed that obesity confers a more inflammatory phenotype on OA synovial tissue, with increased expression of IL-6 and IL-8." (PMID 34201564, 2021). "Adipocytes and macrophages produce also IL-6, which expression is enhanced in obesity." (PMID 34069933, 2021). "This increases the probability of Arid5a involvement in IL6 inhibition of adipogenesis and obesity." (PMID 35126382, 2021). "In asthma, elevated serum IL-6 has been found associated with increased body weight, with lower lung function and greater exacerbation risk independent of obesity." (PMID 33418879, 2021). "They concluded that obesity could alter the ASCs phenotype to confer undesired RT resistance via enhanced secretion of leptin by ASCs, promoted the production of IL-6, and activated Notch pathways in these BC cells." (PMID 34350120, 2021).
Obesity (continued). "In addition to altered levels of leptin and adiponectin, increased levels of obesity-related adipokines such as interleukin-6 (IL-6), interleukin-8 (IL-8), tumor necrosis factor-α (TNF-α), visfatin and resistin are associated with increased cancer risk." (PMID 33987528, 2021). "Compared with the Con group, the Obesity group exhibited an increased oxidative damage and inflammatory response in placenta, as evidenced by the increased concentrations of placental reactive oxygen species (ROS), protein carboxyl, and interleukin-6 (IL-6)." (PMID 34497775, 2021). "Leptin, TGF-β1, and TLR4 pathway through PREP1 reduction or increased IL-6 expression could be promising new biological markers and therapeutic targets in obesity-related diseases." (PMID 34327205, 2021). "Additionally, it has been reported that individuals with high levels of C-peptide, interleukin-6 (IL-6), tumor necrosis factor-α (TNF-α), as well as low level of adiponectin had significantly higher risk of ccRCC, all these biomarkers are obesity-related." (PMID 34621242, 2021). "Moreover obesity elicits macrophage polarization toward the M1 class which produce the pro-inflammatory cytokines IL-6, IL-1β, and TNFα." (PMID 35126181, 2021). "In addition, knowing that obesity itself results in an inflammatory state in metabolic tissues, the release of inflammatory cytokines IL-6, IL-8 and TNF-α from infected lung tissues can exacerbate the pro-inflammatory picture in patients." (PMID 34684105, 2021). "The mechanistic pathway implicated in obesity‐related hypercoagulability includes the actions of adipocytokines, coagulation factors hyperactivity and increased inflammation (tumour necrosis factor [TNF], interleukin‐6 [IL‐6]) among others." (PMID 32904932, 2021). "Interestingly, the IL-6 and TNFα levels are significantly higher in adipose tissue than in liver, in patients with severe obesity, suggesting that adipose tissue is the main cytokine source in the progression of steatohepatitis." (PMID 34073834, 2021). "Thus, in inflammatory conditions such as obesity and type 2 diabetes, immune cells (via increased IL-6) are stimulated to produce neurotrophins, like BDNF, to minimize the neuronal damage associated with obesity." (PMID 34957187, 2021). "Because IL-6 is a cytokine widely recognized to play a major role in obesity and is also known to exert dichotomic effects on IDO1 expression, we investigated the possible effect of the cytokine on IDO1 expression and activity in the WAT of diet-induced obese mice." (PMID 34394118, 2021). "IL6 expression was increased in the hypothalamus of obesity-resistant mice." (PMID 34465367, 2021). "Obesity, particularly visceral adiposity, is associated with chronic low-grade inflammation, as indicated by increased levels of the inflammatory markers CRP and interleukin (IL)-6 in the circulation of obese subjects." (PMID 34828861, 2021). "Thus, we report here that endothelial NOX5 expression under obesity conditions stimulates lipolysis by promoting AMPK phosphorylation mediated by IL-6 production." (PMID 35052534, 2021). "In agreement, the lower promoter methylation profiles found in obese subjects were associated with higher pro-inflammatory cytokines IL-6 and TNF-α plasma levels that play crucial roles in an obesity-associated increased risk of diabetes and cardiovascular diseases." (PMID 34869683, 2021). "A recent study examined the relationship between IL-6 plasma levels with asthma and obesity." (PMID 33418879, 2021). "Our study, reporting the lack of a relationship between obesity parameters (BMI and fat%) and IL-6 polymorphisms rs1800795, rs1800796 and rs13306435 in a homogenous population poses an additional voice in this discussion." (PMID 34680892, 2021). "Furthermore, the exacerbated levels of interleukin (IL)-6 and leptin in obesity result in the downstream activation of STAT3 signaling, which is closely associated with insulin resistance." (PMID 33808960, 2021).
Obesity (continued). "However, we focused that obesity results in a chronic low-grade inflammatory state, with increased pro-inflammatory cytokines, TNF-α and IL-6, causing the activation of stress-induced MAPK signaling." (PMID 34064531, 2021). "In the present review, it can be observed that in adults with overweight or obesity, ET training causes a decrease in circulating levels of IL-6 (from −2 to −56%) in 11 of 13 studies, regardless of exercise-induced fat mass loss." (PMID 34948868, 2021). "IL-6 levels are elevated in the adipose tissues of patients with diabetes mellitus or obesity, particularly in those with MS symptoms, suggesting that IL-6 could be used as a prognostic indicator for MS and cardiovascular dysfunction." (PMID 34680097, 2021). "In contrast, the poor response seen in Cluster E may be explained by its highest observed BMI levels and possible systemic inflammation from increased levels of several obesity-associated cytokines (TNF-α, IL-6, and leptin)." (PMID 33705484, 2021). "In obesity, the adipose tissue becomes hypertrophic and hyperplastic, triggering increased production of pro-inflammatory adipokines, such as tumor necrosis factor α, interleukin 6, interleukin 1, and leptin." (PMID 34283044, 2021). "However, the mechanisms responsible for elevated IL-6 in adipocytes or ATM under obesity remain largely unexplored and merit further investigation." (PMID 34504646, 2021). "IL-6 secreted by T cells, macrophages, and adipocytes plays a key role in the development of insulin resistance and atherosclerosis, pathologies related to obesity and metabolic syndrome." (PMID 32023901, 2020). "Expression of TNF-α and IL-6 are increased in obesity and insulin resistance." (PMID 32796637, 2020). "On the other hand, and in agreement with the literature that reports some relationship between MUFAs and disorders related to obesity, MUFA concentrations of SAT-C14:1, SAT/VAT-C16:1, SAT/VAT-C17:1, VAT-C18:1, and VAT-20:1 were also positively associated with plasma IL-6 concentrations." (PMID 32178673, 2020). "The interaction among obstructive sleep apnea syndrome (OSAS) severity, sex, and obesity on cardiovascular risk as determined by serum levels of C-reactive protein (CRP), interleukin-6 (IL-6), and tumor necrosis factor-α (TNF-α) remains unclear." (PMID 32629899, 2020). "In addition, Xu caught sight of mast cells playing a key role in diet-induced obesity and diabetes for reducing mast cell and macrophage infiltrations and inflammatory cytokine levels and inhibiting mast cell-derived IL-6 expression." (PMID 33292335, 2020). "Prebiotics, particularly inulin and oligofructose, have been shown to increase Bifidobacterium, which has beneficial metabolic effects, such as reducing body fat, serum triglycerides, and the proinflammatory marker interleukin-6 (IL-6) in children with overweight or obesity." (PMID 32708167, 2020). "Furthermore, a study in 446 children (aged 6–12 years) found that TNF-α, IL-6, and IL-8 increased in children with obesity compared to the NW group and that inflammation and anthropometric and metabolic features are independent risk factors for CVD." (PMID 33299523, 2020). "TNF-α and IL-6 secreted by adipocytes up-regulates PD-L1 in hepatoma and B16-F1 cells, which may be at least partially involved in the role of obesity in promoting tumor progression." (PMID 32477009, 2020). "This supports the hypothesis that the activation of IL-6/STAT3 promotes the senescence of BMSCs in BM, suggesting a potential mechanism for trabecular bone loss in HFD-induced obesity." (PMID 33679606, 2020).
Obesity (continued). "Increased concentration of IL-6, secreted by adipocytes and monocytes and activated through the TLR4-NF-κB pathway, has been classically associated with proinflammatory responses and insulin resistance in obesity." (PMID 32604889, 2020). "Previous studies have shown that the Mediterranean diet may be associated with improved blood lipids, lower blood pressure, less obesity, lower insulin resistance and reduced parameters of inflammation like hsCRP and IL-6." (PMID 33266308, 2020). "We have addressed the possibility that blocking IL-6 trans-signaling in the brain could have an effect in the triple transgenic 3xTg-AD mouse model of AD and/or in obesity progression, by crossing 3xTg-AD mice with GFAP-sgp130Fc mice." (PMID 32630818, 2020). "In addition, the consumption of green tea reduced the imbalanced production of cytokines such as TNF-α, IL-1β, and IL-6 in the cortex, cerebellum, and brainstem in obesity-induced mice." (PMID 33312340, 2020). "Macrophage secreted-adipokines such as TNF-α and IL-6 can induce low grade inflammation; thus, obesity could lead to insulin resistance (IR), increased leptin, and decreased adiponectin." (PMID 32961822, 2020). "Moreover, other obesity-induced inflammatory mediators such as TNFα, IL-1 family, and IL-6 have also exhibited the ability to promote insulin resistance." (PMID 32971975, 2020). "Though recent studies have shown an increase in TNF-α and IL-6 levels due to the state of inflammation related to overweight and obesity, the consumption of 60 g/day of cheese, following a balanced and hypocaloric diet, kept these levels stable at the end of the intervention period." (PMID 32380746, 2020). "Unlike TNF-α, IL-6 principally secreted in an endocrine (systemic) fashion and the expanding AT in obesity may contribute high levels of IL-6 in the circulation." (PMID 32893859, 2020). "As both IL-6 and CRP are biomarkers of obesity-associated inflammation, this raises the possibility that obesity may impair immunotherapeutic efficacy in patients with breast cancer." (PMID 33123173, 2020). "Recent in vivo studies in models of obesity and human studies have indicated that αT supplementation was capable of attenuating inflammatory processes by reducing the expression of IL-6, TNF-α, malondialdehyde and C reactive protein while increasing antioxidant constituents." (PMID 32903449, 2020). "Thus, IL6-KO mice develop mature-onset obesity, whereas transgenic mice overexpressing IL-6 in astrocytes (GFAP-IL6 mice) are resistant to HFD-induced obesity." (PMID 32630818, 2020). "In obesity, it can directly or indirectly affect immune tolerance by altering the secretion of adipokines (mainly leptin, adiponectin, and mucin) and/or cytokines (interleukin-6, tumor necrosis factor alpha, and interleukin)." (PMID 32256575, 2020). "This could be explained by previous reports of a positive association between IL-6 level and the presence of OSA and also between IL-6 level and obesity and insulin resistance." (PMID 32093397, 2020). "Moreover, IL-6 also facilitates the alternative activation of macrophages that have been restrained in tissues by obesity-induced insulin resistance and inflammation." (PMID 32295130, 2020). "Specific depletion of myNK cells led to reduced inflammation, obesity, and systemic insulin resistance, which could also be recapitulated through abrogation of IL-6 and STAT-3 signaling that is required for the formation of these unique cells." (PMID 32499756, 2020). "Researches are still in progress and it would be intriguing to investigate whether people with obesity and higher circulating IL-6 levels, compared with lean controls, respond more favourably to IL-6 inhibition strategies in SARS-CoV-2 pandemic." (PMID 33160363, 2020). "Research has confirmed that IL-6 is increased in obesity, a low chronic inflammatory state, and could decrease serum iron level by inducing the expression of hepcidin and downregulating SI via the JAK2-STAT3 signal pathway." (PMID 33292270, 2020).
Obesity (continued). "Consistent with our results that obesity was associated with elevated serum levels of CRP and IL-6 independently of OSAS severity and sex, several studies have also reported increases in both CRP and IL-6 levels in overweight and obese patients regardless of sex." (PMID 32629899, 2020). "Furthermore, there are multiple factors, particular obesity, increase the levels of adipocytes, inflammatory cytokines (IL-1, IL-6, and TNFα)." (PMID 32982969, 2020). "The obesity models were established with WT and IL-6 KO mice after HFD for 12 weeks." (PMID 33679606, 2020). "However, Chu and Li32 concluded that the increases in TNF-α and IL-6 are mainly influenced by the obesity factor." (PMID 30213594, 2020). "Another study showed that accumulation of inflammatory cells and adipocytes results in increased secretion of cytokines like tumor necrosis factor alpha (TNF-α) and interleukin-6 (IL-6) and lead to the progression of metabolic syndrome, consequently worsening the outcome of obesity." (PMID 33042134, 2020). "Indeed, obesity predisposes to a pro‐inflammatory state via increased inflammatory mediators, such as TNF‐α and IL‐6, which stimulate the liver to synthesize and secrete C‐reactive protein." (PMID 33053604, 2020). "This links IL-6 stimulation of T-cells with pathological wound healing in obesity and diabetes." (PMID 32365896, 2020). "TNF-α and IL-6 have been proposed as a link between obesity and insulin resistance." (PMID 32911750, 2020). "As the level of inflammation increases, the state of obesity and therefore percentage body fat also progresses; thus, we evaluated the relationship between the gene expression levels of IL6 and TNFα against the percentage body fat of chow (C)- and high-fat (HF)-fed mice in gWAT, iWAT, iBAT and PAT." (PMID 32580292, 2020). "Obesity as a risk factor for tooth loss may be modified by systemic markers of inflammation such as CRP and IL-6, especially in men." (PMID 32486269, 2020). "Increased secretion of IL-6 is associated with excessive sleeping at day cycle and fatigue, while a reduction of IL-6 secretion is associated with sufficient sleeping at night cycle, whereas both TNF-α and IL-6 secretions have been reported to increase in sleep apnea independently of obesity." (PMID 33050331, 2020). "In obesity, elevated level of IL-6 may lead to a low-grade inflammatory state and bone metabolism imbalance, but the mechanism remains unclear." (PMID 33679606, 2020). "Moreover, inflammatory markers that allow monitoring of obesity and MetS include proinflammatory cytokines production such as TNF-α, IL-1β, and IL-6, which are mainly produced by the macrophages infiltration induced by obesity in the adipose tissue." (PMID 32178436, 2020). "IL-6 stands out among the mediators involved in the pathogenesis of obesity." (PMID 32893859, 2020). "Thus, the downregulation of Il6 and TNFα secretion by V. opulus is relevant not only for bone metabolism but it also has an impact on obesity state, contributing to osteoporosis delay." (PMID 32664580, 2020). "IL-6 was also detected in white adipose tissues in cases of obesity and insulin resistance." (PMID 33425000, 2020). "Furthermore, previous studies have confirmed that serum IL-6 levels are positively correlated with higher BMI scores as a proxy for obesity." (PMID 32793188, 2020). "T2D, often combined with obesity, induces hormonal changes by increasing insulin resistance, inflammation with increased Interleukin 6, and increased reactive oxygen species, all of which can lead to hyperinsulinemia and insulin-stimulated mitosis by directly affecting cancer cell proliferation." (PMID 32369516, 2020). "Moreover, skeletal muscle myocytes can express and secrete numerous cytokines such as IL-6, IL-15, and other molecules such as irisin and myonectin, whereas most adipokines are pro-inflammatory, regulated by obesity." (PMID 32272881, 2020).